CDC42 (cell division cycle 42)
Diseases named in the same sentence as CDC42 in open-access papers (continued):
Sharing a sentence is not in itself a finding about the gene and the disease.
melanoma (continued). "Finally, over-expression of eIF6 in primary melanoma cell lines (WM793) induced cdc42 up-regulation and increased motility and invasiveness, thus demonstrating that the tumor-promoting ability of this initiation factor is not restricted to the A2780 cell line." (PMID 25886394, 2015). "It was furthermore shown that Cdc42 is important for VEGF-driven angiogenic effects in melanoma." (PMID 24766647, 2014). "However, with the discovery of the Cdc42(G12V) mutant in patient samples, and because Cdc42 expression results in a poorer prognosis, we hypothesized that Cdc42G12V may be important in melanoma cell growth, invasion and metastasis." (PMID 37114375, 2023). "We hypothesized that PI3K might be an important target downstream of Cdc42(G12V) in melanoma." (PMID 37114375, 2023). "The reliance of WM266-4 cells on ARHGEF9 and CDC42 for the regulation of cell shape suggests that the activation of this pathway, either at the transcriptional or post-translational levels, represents a means by which melanoma tumor cells evolve the ability to metastasize." (PMID 36039362, 2022). "While RHOJ and CDC42 have not been found to be mutated in melanoma, they are often overexpressed." (PMID 35385746, 2022). "The fact that this activator restores the invasive property of WNT5A knockdown melanoma cells led us to conclude that Cdc42 signaling is essential for the WNT5A‐driven invasion of melanoma cells regardless of whether they invade via an amoeboid or mesenchymal mode of migration." (PMID 33969605, 2021). "In addition, CDC42 facilitates the invasion and migration of melanoma cells." (PMID 32310824, 2020). "Therefore, CDC42 inhibitors have been effective in melanoma treatment." (PMID 32310824, 2020). "Indeed, we could show that WNT5A induced activation of Cdc42 also in malignant melanoma Mewo cells and introduction of DN-Cdc42 and -Rac1 inhibited the WNT5A induced release." (PMID 24766647, 2014). "CDC42 can promote the PI3K pathway in several contexts, including integrin/immune complex-stimulated neutrophil, melanoma cells, and mouse oocytes." (PMID 40954218, 2025). "In particular, the activation of small GTPases such as CDC42, RAB17, RAC1, and RAB27A, which regulate cytoskeletal dynamics, is thought to contribute to melanoma progression and metastasis." (PMID 40594379, 2025). "To evaluate the invasive potential of Cdc42 and Cdc42(G12V) in BRAF mutant melanoma cells, we used a Matrigel invasion assay." (PMID 37114375, 2023). "Depleting Cdc42 together with WYC‐209 treatment decreased F‐actin and increased apoptosis in the differentiated melanoma cells when compared with the synthetic retinoid alone." (PMID 36031407, 2022). "SCC is similar to melanoma, except that JNK/SAPK signaling, cell division cycle 42 (CDC42) signaling, and Hippo signaling also appears in the pathway enrichment of the former." (PMID 36338621, 2022). "PAK1/2 were overactivated in BRAFi- and MAPKi-resistant melanomas in vitro, most likely due to the increased expression levels of direct regulators (RAC1 and CDC42) and the PAK themselves." (PMID 35159327, 2022). "DOCK10 activates Cdc42 which in turn leads to phosphorylation of MLC2 by PAK2, driving the amoeboid phenotype in melanoma." (PMID 34196668, 2021). "These are EGFR, ERRFI1, IL6, JAK2, PLXNC1, RGL3 which were found to be upregulated and CBL, CDC42, PIK3R3, STAT3, UBE2D2 and YWHAZ which were found to be downregulated; Melanoma has PLXNC1 as upregulated and TGFA as downregulated gene." (PMID 34764329, 2021). "DOCK10, a Cdc42 GEF, is necessary for amoeboid motility while DOCK3 drives mesenchymal motility and invasion in melanoma cells through Rac1." (PMID 34196668, 2021). "Taken together, our results suggest that low WNT5A signaling in melanoma cells promotes a rounded amoeboid type of invasion, which quite likely serves as a compensatory response to decreased WNT5A/Cdc42‐driven invasion." (PMID 33969605, 2021).
melanoma (continued). "Clinically, CDC42, RAC1, and RHOA expression in patient samples can provide relevant knowledge about melanoma thickness, ulceration, prognosis, and drug resistance." (PMID 33072757, 2020). "A report examining melanoma CSCs described a number of genes that appear to be regulated by ALDH1A1 and/or ALDH1A3, including CDC42, a gene containing RAREs." (PMID 28423611, 2017). "Recent studies have shown that Cdc42 is activated downstream of CD47 and regulates melanoma cell migration." (PMID 27411490, 2016). "When we quantified the number of cells that invaded through the Matrigel insert, we found that melanoma cells expressing Cdc42(G12V), but not Cdc42, migrated significantly more than the vector only control cells." (PMID 37114375, 2023). "Future studies will need to be done to determine whether Cdc42 and PI3K are important oncogenic targets in other melanoma genetic backgrounds." (PMID 37114375, 2023). "CDC42 regulates melanoma invasion and is activated in BRAF-resistant melanoma cells." (PMID 35385746, 2022). "In addition, CDC42 and its downstream p21-activated kinases (PAKs) are regulators of mitogen-activated protein kinase (MAPK) inhibitor resistance in BRAF mutant melanoma." (PMID 35385746, 2022). "Knockdown of WNT5A expression not only decreased melanoma cell invasion but also resulted in a significant reduction in Cdc42 activity but no change in Rac1 activity in either cell line." (PMID 33969605, 2021). "In addition to CDC42 and RAC1 GTPases, RHOA is also part of molecular networks crucial for the control of melanoma proliferation, migration, and invasion." (PMID 33072757, 2020). "As such, pharmacological drugs capable of interfering with CDC42 activity could induce conformational alterations in the actin cytoskeleton, impairing the invasiveness of BRAF-resistant melanoma cells." (PMID 33072757, 2020). "Surprisingly, silencing Cdc42 significantly increased rather than decreased nuclear and cytoplasmic transmigration of control melanoma cells but not TRCs." (PMID 26787224, 2016). "A signaling complex composed of Cdc42, Ack1, and Cas also participates in the regulation of melanoma cell spreading by melanoma chondroitin sulphate proteoglycan (MCSP), a proteoglycan that is expressed on the surface of melanoma cells." (PMID 21637378, 2011). "A melanoma patient-derived xenograft was implanted into the flanks of NSG mice, and when the tumors reached a volume of 150–200 mm3, they were treated with the indicated doses of the CDC42 inhibitor ARN22089, vemurafenib, or vehicle twice daily for 2 weeks by oral gavage." (PMID 40950721, 2025). "Importantly, however, we found that expression of constitutively active Cdc42 did not stimulate detectable lamellipodia formation in the absence of Rac GTPases, in both fibroblasts and B16-F1 melanoma cells." (PMID 35971979, 2022). "Interestingly, a recent study showed that melanoma cell lines resistant to a BRAF inhibitor (PLX4032) display increased CDC42 activity compared to non-resistant melanoma cells." (PMID 33072757, 2020). "However, in BRAFi‐R melanoma cells, no data are available regarding possible altered Cdc42/Rac1‐GTPase activities." (PMID 30582770, 2019). "The noncanonical EPHA2 promoted a switch from RAC1 to CDC42 (and RHOA) to increase the invasion and PI3K-dependent p-MLC2 levels in therapy-naïve melanomas." (PMID 35159327, 2022). "We utilized a Cdc42-PAK functional assay to better evaluate the activation of this family of GTPases in melanoma and determined that RhoJ, Cdc42, and Rac1/2/3 interact with PAK in melanoma cells when they are GTP-bound but not when they are loaded with GDP." (PMID 28753606, 2017).
glioblastoma (36 papers, 2010 to 2024). The most malignant astrocytic tumor (WHO grade IV). "In glioblastoma, the increased activity of Rac1, Cdc42, RhoA, and RhoG is associated with the invasiveness of tumor cells." (PMID 35053605, 2022). "Moreover, CCNB1, MAPK7, CD44, and CDC42 oncogenes have been associated with patients’ clinical outcomes in glioblastoma and it has been identified in simulation studies for druggable candidates of SJ10." (PMID 39409884, 2024). "Most importantly, the function of SOXC factors can be replaced by chemicals targeting RhoA, RAC1, CDC42, or their effectors, indicating a critical role of Rho GTPases played during neuronal reprogramming of human glioblastoma cells." (PMID 39390804, 2024). "In astrocytes and glioblastoma cells RhoGDI1 interacts with the cytoplasmic domain of the β8 integrin subunit of the αvβ8 heterodimer, which limits the activity of Rac1 and Cdc42." (PMID 39086660, 2024). "Similar results were exhibited in glioblastoma cells where ROCK2 KD increased migration by increasing phosphorylation of Cdc42/Rac which regulates actin polymerization and thus plays a central role in cell migration." (PMID 36719899, 2023). "The inhibition of migration of glioblastoma cells after Luteolin treatment was found to be related to the increment in the degradation of Cdc42 protein by activating the proteasome degradation pathway." (PMID 36992138, 2023). "The Rho family of GTPases from the Ras superfamily, Rho-A, Rac1, and Cdc42, are responsible for the spatial regulation of glioblastoma invasion." (PMID 35053605, 2022). "We first related TRPV4 to the Cdc42/N-wasp pathway in glioblastoma and explored the area of the TRP family with cellular protrusion formation." (PMID 32843668, 2020). "Cdc42 is also believed to be a mediator of the X-ray promoted invasion of glioblastoma, a complication that occurs following radiotherapy." (PMID 32089990, 2020). "In conclusion, the TRPV4/Cdc42/wasp signaling axis regulates cellular protrusion formation in glioblastoma cells and influences the invasion-growth phenotype of glioblastoma in vivo." (PMID 32843668, 2020). "According to a biosensor assay done on glioblastoma cells, low Rac1 and low Cdc42 are found on the trailing end while high Rac1 and high Cdc42 levels are found on the leading edge of the cells." (PMID 32089990, 2020). "The Rho family of small GTPases, which includes Rac1, Cdc42, and RhoA, is an important family whose members are key regulators of the invasion and migration of glioblastoma cells." (PMID 32089990, 2020). "In this context, luteolin was found to facilitate the proteasomal degradation of Cdc42, leading to decreased glioblastoma migration and invasion in vitro." (PMID 32089990, 2020). "StarD13 (START-GAP2) is a GTPase-activating protein (GAP) that specifically inhibits RhoA and Cdc42 in glioblastoma cells and other tumor models." (PMID 31698752, 2019). "We found that luteolin inhibited the cell migration of glioblastoma and managed to decrease the protein expression of Cdc42 and F-actin." (PMID 23677714, 2013). "Moreover, Cdc42 has been used as a target for antitumor drugs designed to prevent glioblastoma migration and invasion." (PMID 37174724, 2023). "Because we showed a decrease in the migration capacity of glioblastoma cells under treatment with miR‐218 in our studies, we could conclude then that these changes might be the result of the impact of miR‐218 on CDC42, STAT3, EGF and CTTN." (PMID 35702951, 2022). "We describe a novel CTRP8‐RXFP1‐Janus‐activated kinase 3‐STAT3 signaling cascade that enhances cellular protein content and activity of small Rho GTPase Cdc42, which directs F‐actin cytoskeletal remodeling, filopodia formation, and increased glioblastoma multiforme migration." (PMID 33960104, 2022). "Moreover, STARD13, a GTPase-activating protein (GAP), inhibits RhoA and Cdc42 specifically in glioblastoma cells and other types of tumor models." (PMID 34952924, 2021).
glioblastoma (continued). "We concluded here that TRPV4 regulates Cdc42/N-wasp axis in glioblastoma cells." (PMID 32843668, 2020). "To test whether the Cdc42 mediates the function of TRPV4 in regulating the invasiveness of glioblastoma, we performed Cdc42 inhibitor to treated U87 cell." (PMID 32843668, 2020). "Moreover, 30 μM luteolin inhibits the migration of human glioblastoma U-87 MG and T98G cells through the down-regulation of Cdc42 gene expression and ERK protein phosphorylation." (PMID 28947953, 2017). "Taken together, Cdc42-inhibitors (possibly in combination with anti-angiogenic drugs) may prove therapeutically beneficial not only against primary and recurrent glioblastoma, but also other tumors that co-opt blood vessels during brain metastasis." (PMID 25032689, 2014). "Furthermore, azathioprine’s actions as a guanine antagonist could be antiviral, as reported for Zika virus (ZIKV), where siRNA knockdown of RhoA and Cdc42 was shown to enhance ZIKV infection in glioblastoma cells." (PMID 38054722, 2024). "It was found that Luteolin was able to inhibit the migration of U-87 MG and T98G glioblastoma cells via intervening with the PI3K/AKT activation, downregulating the expression of Cdc42." (PMID 36992138, 2023). "We demonstrate that RNA isolated from pseudopodia of hGCs contains migration-specific transcripts including Cdc42, Cofilin-1, Ezrin, Ilk, Limk, STAT3, MMP2, and Itgb1, recently described as part of intracellular pathways related to glioblastoma migration." (PMID 30353164, 2019). "Conversely, RNAs overexpressed in LTCs vs LTPs showed an enrichment in markers of the neural subtype of glioblastoma, such as BASP1, CDC42, and SH3GL2." (PMID 26188123, 2015). "Taken together, the study demonstrated that flavonoids of luteolin prevent the migration of glioblastoma cells by affecting PI3K/AKT activation, modulating the protein expression of Cdc42 and facilitating their degradation via the proteaosome pathway." (PMID 23677714, 2013). "The pharmacological mechanism of luteolin that inhibits migration of glioblastoma cells is likely to inhibite PI3K/AKT activation and facilitates protein degradation of Cdc42 via the proteaosome degradation pathway." (PMID 23677714, 2013). "In our experiments, Numb5 and Numb6 showed interactions with Cdc42, IQGAP1 and vimentin, a protein expressed in radial glial and glioblastoma cells." (PMID 21122105, 2010). "DOCK7 is a RAC-GEF with the potential to regulate F-actin organization, consistent with previous publications reporting DOCK7-mediated RAC1/CDC42 - PAK1 activation in the DNA replication stress response 122, and the promotion of glioblastoma cell invasion by DOCK7 via RAC activation." (PMID 37064875, 2023). "EHT1864 blocks activation of Rac, but not the related proteins CDC42 or RhoA, at a concentration of 50 μM in glioblastoma cells." (PMID 28423521, 2017). "In addition, we also identified key genes, including MMP9, CD44, CDC42, COL1A1, COL1A2, CAMK2A, and CAMK2B, as potential target genes for diagnosing glioblastoma." (PMID 28191466, 2017). "Regarding the first signature network component, hsa-mir-137, hsa-mir-330, hsa-mir-149, hsa-mir-107, hsa-mir-181b were among the miRNAs whose experimentally validated targets (such as CTBP1, CDC42, CDK6, E2F1, VEGFA, AKT1, KAT2B) affect the pathways which play a crucial role in glioblastoma biology." (PMID 28045122, 2017). "Thus, Cdc42 is vital for TRPV4-mediated invasion and protrusions formation of glioblastoma." (PMID 32843668, 2020). "Consequently, a novel luteolin-mediated inhibitory of migration pathway is proposed that luteolin inhibited the invasion and migration of glioblastoma cells is likely to inhibite PI3K/AKT activation and facilitate protein degradation of Cdc42 via the proteaosome degradation pathway." (PMID 23677714, 2013).
glioblastoma (continued). "Together, these observations indicate a crucial role of the Graf (ARHGAP26)/Rac1/Cdc42 axis, not DOCK180 or ELMO1, in CD151-α3 integrin complex-mediated signaling in glioblastoma." (PMID 26377974, 2015).
prostate carcinoma (34 papers, 2012 to 2025). A carcinoma that arises from epithelial cells of the prostate gland. "Immunohistochemical staining revealed that the increased expression of FASN, RhoU and Cdc42 was associated with prostate cancer aggressiveness." (PMID 32139877, 2020). "Activated cell division cycle 42 (CDC42)-associated kinase Ack1 promotes prostate cancer progression." (PMID 28425476, 2017). "Our results suggest that levels of RhoU and Cdc42 expression in prostate cancer cells are associated and could be correlated with disease progression." (PMID 32139877, 2020). "Western blots also failed to reveal RhoGDI1 and RhoGDI2 loss of expression in the aggressive prostate cancer cell lines that could have explained Rac1 and Cdc42 hyperactivation." (PMID 32092966, 2020). "Integration of these results with the machine learning approaches identified MAPK14 and CDC42 as potential key regulators in prostate cancer progression." (PMID 41246859, 2025). "Small interfering RNA screens targeting Rho GTPases in human prostate cancer cells identified CDC42 as a critical regulator of cancer cell-endothelial cell interaction and intercalation." (PMID 38762624, 2024). "Further, in vitro Fasn inactivation by shRNA affects the adhesion, migration, and invasion of prostate cancer cell lines via actin cytoskeletal remodeling, achieved by decreasing the palmitoylation of the GTPase RhoU and consequent inactivation of Cdc42." (PMID 33166087, 2021). "For example, for metastatic prostate cancer cells, it has been shown that they invade fibroblasts dependent on EphB3 and EphB4 signaling and activation of Cdc42." (PMID 34502237, 2021). "For example, expression of Frabin (FGD4), a GEF specific for Cdc42, positively correlates with the aggressive phenotype of prostate cancer and the tumor grade of pancreatic neuroendocrine neoplasms, most likely by maintaining abnormal activation of Cdc42." (PMID 32664294, 2020). "First, we demonstrated that aggressive androgen-independent prostate cancer cell lines have markedly increased levels of activated Rac1, an effect also observed for the related G-protein Cdc42." (PMID 32092966, 2020). "To test the clinical significance of our findings we analysed FASN, RhoU and Cdc42 in prostate cancer and adjacent benign tissue in a cohort of 85 men who underwent a radical prostatectomy." (PMID 32139877, 2020). "Taken together this analysis strongly suggests the involvement of RhoU and Cdc42 in prostate cancer progression." (PMID 32139877, 2020). "Nintedanib, a tyrosine kinase inhibitor, is suggested to induce entosis in human prostate cancer cells in xenografted mice, along with E-cadherin upregulation and CDC42 downregulation." (PMID 31905803, 2019). "AZA1 downregulates Rac1 and Cdc42 activity in PC-3 human prostate cancer cells and inhibits the proliferation and migration of those cells as well as decreasing formation of lamellipodia and filopodia in which Cdc42 and Rac1 play a crucial role." (PMID 29596304, 2018). "In support of that, we noted a significant decrease (50%) in cell migration in scratch assays and a reduced activation of CDC42 upon inhibition of FGD4 expression in prostate cancer cells." (PMID 30558664, 2018). "We previously demonstrated that ATP induced activation of Rac1 and Cdc42, promoted the formation of lamellipodia and filopodia, and increased the motility of prostate cancer cells, indicating a possible role of P2Y2 receptor in prostate cancer cell motility." (PMID 26182292, 2015). "We now report the identification and biological activity of AZA1, a novel dual Rac1 and Cdc42 inhibitory compound that retards prostate cancer growth effectively in a human prostate cancer xenograft model." (PMID 24040362, 2013). "Deregulated Rho GTPases Rac1 and Cdc42 have been discovered in various tumors, including prostate and Rac protein expression significantly increases in prostate cancer." (PMID 24040362, 2013).